MB (myoglobin)
Diseases named in the same sentence as MB in open-access papers (continued):
Sharing a sentence is not in itself a finding about the gene and the disease.
COVID-19 (continued). "Plasma levels of iron homeostasis markers Fec and myoglobin were higher in COVID-19 compared to HC (but not different from PO), while lactoferrin was lower in COVID-19 compared to HC." (PMID 37582864, 2023). "Moreover, we identified seven possible pharmacological targets of vitamin D against COVID-19/HCC, including HMOX1, MB, TLR4, ALB, TTR, ACTA1 and RBP4." (PMID 36275701, 2022). "Our results are supported by observations in non-pregnant critical COVID-19 patients for whom cardiac biomarkers (troponin I, troponin T, creatine kinase-MB, and myoglobin) predict poor prognosis." (PMID 35215865, 2022). "A meta-analysis reports significant differences in LDH between severe and nonsevere COVID-19 patients while changes in CK and other muscle biomarkers (e.g., troponin I and myoglobin) were not significant." (PMID 34113379, 2021). "More importantly, multivariate Cox analysis showed that myoglobin, rather than hs-TnI or CK-MB, was independently prognostic for in-hospital mortality in COVID-19." (PMID 34458331, 2021). "In the current study, creatine kinase-MB was elevated in only three patients in the T2DM group and none in the non-T2DM group suggesting that the combined effect of DM and COVID-19 might have led to increased troponin T levels even in the absence of ischaemic injury." (PMID 37976296, 2023). "Further, we identified seven overlapping genes of vitamin D against HCC and COVID-19 using the network pharmacology approach, and the anti-COVID-19/HCC effects of vitamin D may be modulated by these molecules or genes, including HMOX1, MB, TLR4, ALB, TTR, ACTA1 and RBP4." (PMID 36275701, 2022). "Although sporadic studies have shown that myoglobin may have better prognostic performance than other cardiac markers in COVID-19, a comprehensive comparative study is lacking." (PMID 34458331, 2021). "The Chinese national guidelines for the diagnosis and treatment of COVID-19 state that it is common for patients to have a normal or decreased WBC count, a and decreased neutrophil count; that some patients have increased LDH, and myoglobin; and that most patients have an elevated CRP." (PMID 32502054, 2020). "Compared to COVID-19 patients without DM, the levels of C-reactive protein (CRP), myoglobin, alanine transaminase (ALT), and aspartate aminotransferase (AST) were significantly increased in DM patients." (PMID 33381599, 2020).
renal failure (41 papers, 2005 to 2026). "One of the most prominent pathogenic effects of extracellular metHb and myoglobin is their potential to cause kidney failure." (PMID 36774392, 2023). "The loss of blood in trauma patients leads to secondary renal insufficiency and impaired excretion, which together with the accumulation of myoglobin in the renal tubules leads to reduced renal function." (PMID 23705945, 2013). "This could be due to dehydration and secondary pre-renal insufficiency and/or renal insufficiency caused by tubular necrosis due to the release of myoglobin during rhabdomyolysis." (PMID 33033722, 2020). "As excessive excretion of myoglobin can lead to kidney damage and even kidney failure because of its toxic effect on renal tubules, the level of myoglobin in serum plays an additional important role for diagnostics in sports medicine." (PMID 37204619, 2023). "Regarding predictors for amputation, beside elevated myoglobin levels and renal insufficiency, interestingly, combined arterial and venous injury of the popliteal area showed a trend towards higher amputation rates." (PMID 36449024, 2023). "Rhabdomyolysis is a potentially life-threatening condition in which skeletal muscle breaks down, resulting in the release of myoglobin and creatine kinase (CK) in the blood; CK accumulation can lead to kidney failure and death." (PMID 36381889, 2022). "We found that a dominantly parenchymal type of kidney failure was characterized by myoglobin toxicity on the tubular cells, and systemic acidic load, postconditioned animals expressed less severe myoglobin-induced tubular injury and a better compensated acid–base status." (PMID 25622967, 2015). "For example, increased plasma carbonic anhydrase activity could contribute to the impairment of the acid-base and excess myoglobin in blood circulation could lead to kidney failure if filtrated by kidneys." (PMID 24743550, 2014).
kidney damage (27 papers, 2014 to 2025). "Rhabdomyolysis‐induced muscle damage leads to the release of myoglobin into the bloodstream, which causes kidney damage, generates free radicals, and elevates proinflammatory cytokines such as TNF‐α." (PMID 39803217, 2025). "These can lead to muscle cell destruction and the release of myoglobin, potentially causing kidney damage." (PMID 39872682, 2025). "As a small-molecule protein, myoglobin can precipitate in the glomerular filtrate, particular in the acidic condition and hypovolemia, finally causing severe kidney damage." (PMID 35273980, 2022). "A single HIIRT session caused early and significant elevations in CK, myoglobin, SCr, microalbuminuria and urinary biomarkers indicative of kidney tubular injury, suggesting the occurrence of muscle and kidney damage." (PMID 30399190, 2018). "Although presumably contributing independently, it remains unclear whether direct myoglobin-related kidney damage is the main mechanism relating CPK levels with the risk for AKI." (PMID 35207410, 2022). "Moreover, pronounced dehydration associated with influx of muscle protein (myoglobin) caused by muscle damage may lead to kidney damage." (PMID 33810371, 2021). "If systemic acidosis is present, sodium bicarbonate should be given to raise urine pH above 6.5 to reduce myoglobin-induced kidney damage." (PMID 39544555, 2024). "Human kidney biopsy sample of patient with severe rabdomyolysis morphologically corresponded to myoglobin cast nephropathy with all features of AKI." (PMID 36140438, 2022). "The plugging of distal convoluted tubule with casts was similar to that seen in myeloma and myoglobin cast nephropathies." (PMID 34514566, 2021). "The plugging of DCT with casts was similar to that seen in myeloma and myoglobin cast nephropathies." (PMID 34514566, 2021). "If systemic acidosis is present, sodium bicarbonate should also be administered to ensure urine pH is higher than 6.5 to minimize myoglobin-induced kidney damage." (PMID 32983728, 2020). "Previous studies have suggested that the accumulation of myoglobin (Mb) in the kidney is the core mechanism leading to kidney damage." (PMID 31781351, 2019). "Within this framework, rapid reduction of circulating myoglobin may interrupt pigment-nephropathy before established tubular injury." (PMID 41398626, 2025). "Thus, based on clinical, laboratory, and histological evidence, a diagnosis of myoglobin-induced nephropathy was made." (PMID 39130933, 2024). "It further remains unclear whether and how much myoglobin elimination leads to less kidney damage and faster completion of dialysis." (PMID 33509234, 2021). "However, inefficient removal of myoglobin also results in a persistent high circulating level of the molecule with kidney damage and delay in renal function recovery." (PMID 25043142, 2014). "Presence, location and extent of PAX8 expression were analyzed among 31 human kidney samples of AKI (25 autopsy cases, 5 kidney biopsies with unknown etiology and 1 AKI with confirmed myoglobin cast nephropathy), as well as in animals with induced postischemic AKI." (PMID 36140438, 2022). "However, as the primary muscle damage was the same in both groups at 24 h, which indicates the same myoglobin-induced kidney damage, we could assume that the majority of PL’s nephroprotective effects were associated with direct impact on the kidneys." (PMID 36293129, 2022). "However, the authors speculate that RM-induced kidney damage involves direct interaction of myoglobin with mitochondria possibly resulting in iron ion release from myoglobin’s heme, and this promotes the peroxidation of mitochondrial membranes." (PMID 25043142, 2014). "The factors leading to kidney damage induced by EHS mainly include prerenal dehydration, blockage of postrenal myoglobin, renal vessels (microthrombosis), renal interstitium (inflammation), and some undetermined relevant factors." (PMID 34839765, 2021).
kidney damage (continued). "Laboratory results showed that myoglobin and CK levels were the most common abnormal indicators, and most patients demonstrated significant liver function abnormalities without obvious kidney damage." (PMID 38765823, 2024).
diabetes (25 papers, 2006 to 2026). "In univariate analysis, NT-proBNP, NT-proBNP/troponin ratio, CK-MB, myoglobin, age, C-reactive protein and non-insulin dependent diabetes mellitus (NIDDM) were associated with CLTI (all p < 0.05)." (PMID 40299905, 2025). "We found that patients with acute respiratory failure often returned to the hospital, with pneumonia, diabetes, and myoglobin being identified as the most significant risk factors." (PMID 38355552, 2024). "hs-TnT, CK-MB and myoglobin are associated with chronic diseases such as diabetes and end-stage renal disease." (PMID 35265036, 2022). "Ultimately, three independent risk factors were retained: Myoglobin, Diabetes, and Pneumonia." (PMID 38355552, 2024). "In this review, we have discussed how heme-irons of hemoglobin and myoglobin can promote oxidative stress under different pathophysiological conditions including metabolic syndrome, diabetes, cardiovascular, neurodegenerative and renal diseases." (PMID 40070406, 2025). "The LASSO analysis retained 11 variables with non-zero coefficients: Glutamyltransferase, triglyceride, total cholesterol, myoglobin, lactic acid, carboxyhemoglobin, respiratory failure type, diabetes, cardiovascular disease, asthma, and pneumonia." (PMID 38355552, 2024). "On the basis of model simulations, the contribution of myoglobin oxygenation to total heme oxygenation can be significantly different under pathophysiological conditions, such as diabetes and peripheral arterial disorder." (PMID 37481476, 2023). "Our findings of an association between myoglobin and DKD suggest that myoglobin, in addition to its use in acute kidney injury, maybe a marker of slowly deteriorating kidney function in diabetes patients." (PMID 31805809, 2020). "We also found several categories of genes not previously associated with insulin resistance or diabetes, namely, genes involved in ribosomal function and oxygen sensing (myoglobin and hemoglobin)." (PMID 17178004, 2006). "Surprisingly, the one-year follow-up mortality rate was influenced by other variables, such as age, history of type 2 diabetes mellitus, HDL-cholesterol levels, C-reactive protein levels, and myoglobin levels." (PMID 22536511, 2012). "Laboratory parameters, including the serum urea nitrogen, high-sensitivity cardiac troponin I, myoglobin, D-dimer, lactate dehydrogenase, procalcitonin, C-reactive protein, and ferritin levels, were markedly higher in patients with diabetes than in those without diabetes." (PMID 33776910, 2021). "Conversely, four biomarkers showed higher serum levels in those without diabetes (CT-1, LDH-B, FABP-3, and myoglobin)." (PMID 39772209, 2024).
iron deficiency (25 papers, 2014 to 2026). "Iron, a necessary component of hemoglobin and myoglobin, is essential in hemoglobin synthesis and erythroid cell proliferation, and iron deficiency leads to anemia." (PMID 39474425, 2024). "It is well known that iron deficiency in the skeletal muscle is associated with reduced a concentration of myoglobin, which has an impact on tissue physiology." (PMID 37629065, 2023). "Because iron is the principal component of hemoglobin, myoglobin, and several enzymes, iron deficiency is connected to lower resistance to infection, reduced productivity, fatigue, and fetal mortality." (PMID 37038224, 2023). "Iron deficiency caused anaemia, decreased cytochrome c in multiple tissues, and lowered myoglobin in muscle." (PMID 35249268, 2022). "This is of interest also because iron deficiency has been associated with reduced myoglobin and cytochrome c resulting in impaired skeletal muscle oxidative capacity." (PMID 35249268, 2022). "In this study, we also showed that iron feeding in non‐anaemic dystrophic mice increased cytochrome c and myoglobin, potentially rescuing a functional iron deficiency." (PMID 35249268, 2022). "Iron is required for the formation of hemoglobin, myoglobin, and heme enzymes, so iron deficiency leads to impaired hemoglobin synthesis, resulting in hypochromic, microcytic anemia." (PMID 34362147, 2021). "The percentage of runners with hematuria, leukocyturia, iron deficiency, creatinine, myoglobin, and bilirubin imbalance was higher in RR compared to XX genotypes." (PMID 31244673, 2019). "Iron deficiency also affects the production of other iron-containing proteins, such as cytochrome, myoglobin, catalase, and peroxidase." (PMID 26527217, 2015). "Iron deficiency should be avoided because it causes anemia (hemoglobin) and muscle weakness (myoglobin)." (PMID 25221514, 2014). "Iron on the other side is a critical element for hemoglobin and myoglobin synthesis, oxygen transport, and numerous redox enzymes, while its deficiency remains one of the most widespread nutritional disorders worldwide, leading to iron-deficiency anemia, fatigue, and impaired cognitive development." (PMID 41517208, 2026). "When myoglobin levels decrease, the tolerance of cardiomyocytes to hypoxia is reduced, especially during acute ischemia or after MI, further exacerbating the hypoxic state under iron deficiency." (PMID 39669378, 2024). "Iron deficiency affects mitochondrial metabolism and myoglobin synthesis which may impair muscle performance." (PMID 38438954, 2024). "Among the micronutrients, iron deficiency is most likely, and inadequate iron status can impair exercise performance through suboptimal haemoglobin levels and changes in the muscle, including a reduction in myoglobin and iron-related enzymes." (PMID 39599736, 2024). "Second, iron deficiency adversely affects myocardial performance by impacting the expression and function of key proteins involved in oxygen transport and utilization, such as myoglobin and cytochrome c oxidase (COX)." (PMID 39669378, 2024). "In another study, different factors had been diagnosed for explaining the association between overweight/obesity and iron deficiency including inadequate physical activity, genetic factors, poor and unhealthy diets, and less releasing of iron as a consequence of decreased myoglobin breakdown." (PMID 36817069, 2022). "Iron deficiency independently of anemia negatively affects oxidative metabolism, cellular energetic and immune mechanisms which result in decreased oxygen storage in myoglobin and reduced myocardial oxygen capacity leading to mitochondrial and left ventricle dysfunction." (PMID 37074386, 2023). "Another mechanism for the impact of dietary iron intakes on frailty is that iron deficiency without anemia can affect iron-containing compounds other than hemoglobin involved in energy production (myoglobin, oxidative enzymes, and respiratory chain proteins)." (PMID 35352124, 2022).
iron deficiency (continued). "It is also important to correct iron deficiency without anaemia, as iron deficiency leads to the reduced availability of myoglobin and the dysfunction of mitochondria in skeletal muscle, with myoglobin and correctly functioning mitochondria both being essential for exercise prehabilitation." (PMID 38436470, 2024). "Iron deficiency without anemia (ID) is a preclinical stadium for iron deficiency anemia (IDA), and already at this stage may have deleterious effects: deranged mitochondrial function; impaired synthesis of Hb, myoglobin, cytochromes, nitric oxide synthase; and impaired immune function." (PMID 37002279, 2023).
anemia (22 papers, 2014 to 2026). A reduction in the number of red blood cells, the amount of hemoglobin, and/or the volume of packed red blood cells. "As one of the most abundant trace elements in the body, iron plays an important role in Hb synthesis as well as myoglobin oxygen transport, which predisposes the body to anemia when iron absorption or intake is inadequate." (PMID 41156473, 2025). "Myoglobin, the protein that carries oxygen to muscle tissue, is affected by anemia, generating local hypoxia in skeletal muscle." (PMID 38544759, 2024). "The decrease in iron content in anemia patients affects mitochondrial metabolism and myoglobin synthesis, consequently impairing muscle performance." (PMID 39118670, 2024). "In general, adolescents are recognized as a population that is vulnerable to anemia, given the increased requirements of nutrition for growth, and, more specifically, the increased iron requirements for myoglobin in muscles and hemoglobin in the blood." (PMID 35883960, 2022). "When heme increases, heme iron in myoglobin also increases, which may finally increase a* and decrease L* under extreme anemia conditions." (PMID 32947784, 2020). "The most commonly reported adverse effects were hematological (especially leukopenia, as well as thrombocytopenia and anemia), fatigue, fever, hypotension (this was transitory and treated with vasopressors, associated in some studies with TNF-α leaks), and the mild elevation of myoglobin." (PMID 34771649, 2021).